ALDH1A3 (aldehyde dehydrogenase 1 family member A3)
Diseases named in the same sentence as ALDH1A3 in open-access papers (continued):
Sharing a sentence is not in itself a finding about the gene and the disease.
diabetes (9 papers, 2016 to 2025). "Being a metabolic enzyme, ALDH1A3′s association with metabolic diseases, including diabetes, is predictable and there is growing evidence of its effects on glycometabolism." (PMID 36672441, 2023). "The dearth of differences between wild-type and Foxo-deficient ALDH+ cells is wholly consistent with the concept that in diabetes there is a ‘spontaneous' loss of Foxo6, 7, 8, and that Foxo normally restrains ALDH1A3 expression." (PMID 27572106, 2016). "Therefore, lineage tracing of A+ cells demonstrates that improvement of diabetes in Pair-fed responder db/db mice is associated with reversal of ALDH1A3 activation, whereas worsening β-cell failure is associated with an increase in A+ cells." (PMID 36732513, 2023). "This allows us to speculate that the energy status of the cell is associated with ALDH1A3 and its potential role in metabolic reprogramming in disease conditions, such as cancer, diabetes and obesity." (PMID 35418200, 2022). "It has been shown previously using a mouse model of diabetes that there is a striking upregulation of ALDH1A3 in a subset of dedifferentiating beta cells." (PMID 39762647, 2025). "To tackle these questions, we (i) investigated the fate of A+ cells during pair-feeding by lineage-tracing, (ii) somatically ablated ALDH1A3 in diabetic β-cells, and (iii) used a novel selective ALDH1A3 inhibitor to treat diabetes." (PMID 36732513, 2023). "Our data showed that the main metabolic defects, which occur in diabetes, impact the cell machinery by altering ALDH1A3 gene expression, among others." (PMID 37511575, 2023). "Here, the authors show evidence of re-differentiation of de-differentiated β-cells and identify ALDH1A3 as a key player in this process, proposing inhibition of ALDH1A3 as a treatment method for β-cell dysfunction in diabetes." (PMID 36732513, 2023). "In summary, the current work advances the field by showing the reversibility of β-cell dedifferentiation at the ALDH1A3 activation stage and providing proof-of-principle in preclinical models of its pharmacological inhibition as a treatment for diabetes." (PMID 36732513, 2023). "We conclude that ALDH1A3 inhibition offers a therapeutic strategy against β-cell dysfunction in diabetes." (PMID 36732513, 2023). "We tested the expression of ALDH1A3 in other models of diabetes including aging, diet-induced and db/db mutants, and found it to be increased too." (PMID 27572106, 2016). "ALDH1A3 ablation may therefore improve or reverse diabetes in mice." (PMID 36732513, 2023). "The number of ALDH1A3-positive (a biomarker of β-cell dedifferentiation), insulin-negative cells was threefold higher in individuals with diabetes." (PMID 41473243, 2025). "On the other hand, it is conceivable that cellular ATP levels may modulate ALDH1A3 activity by a negative feedback mechanism, similarly to some enzymes participating in the glycolytic pathway, which may be relevant in other disease states such as obesity and diabetes." (PMID 35418200, 2022).
gastric cancer (9 papers, 2016 to 2025). A primary or metastatic malignant neoplasm involving the stomach. "In gastric cancer, ALDH1A3 causes 5-fluorouracil and cisplatin resistance in connection with the histone demethylase and oncogene Lysine Demethylase 4C (KDM4C)." (PMID 36672441, 2023). "Inhibition of the ALDH1A3-mTOR axis with an mTOR inhibitor, temsirolimus, eradicated 5FU-tolerant gastric cancer cells." (PMID 41304766, 2025). "We previously demonstrated that ALDH1A3 expression is commonly upregulated by anticancer drugs in multiple gastric cancer PDC lines and mouse xenograft models." (PMID 38669046, 2024). "To examine the effect of ALDH1A3 upregulation on cancer growth in vivo, we exogenously overexpressed ALDH1A3 in the gastric cancer PDC line JSC15-3 and subcutaneously implanted it into NOD-SCID mice." (PMID 38669046, 2024). "In this study, we demonstrated epigenetic induction of ALDH1A3-overexpressing gastric cancer DTP cells after chemotherapy." (PMID 38669046, 2024). "We found that gastric cancer tissues treated with neoadjuvant chemotherapy showed high ALDH1A3 expression." (PMID 38669046, 2024). "To elucidate the mechanism of 5-FU–induced generation of gastric cancer persister cells, we conducted chemical screening for compounds that interfered with the generation of ALDH1A3-overexpressing DTP cells." (PMID 38669046, 2024). "Here, we investigated the mechanism of ALDH1A3 expression and a combination therapy targeting gastric cancer DTP cells." (PMID 38669046, 2024). "Aldehyde dehydrogenase 1 family member A3 (ALDH1A3) is commonly upregulated by various anticancer drugs in gastric cancer patient-derived cells (PDC) and promotes tumor growth." (PMID 38669046, 2024). "In the gastric cancer PDCs examined in this study, most cells converted to ALDH1A3high cells after 5-FU treatment, whereas ALDH1A3 induction remained heterogeneous in the cancer cell population." (PMID 38669046, 2024). "In turn, ALDH1A3 increases KDM4C levels, thereby establishing a KDM4C-ALDH1A3 feedforward regulation which results in chemoresistance in gastric cancer." (PMID 36672441, 2023). "mTOR pathway is the downstream mediator of ALDH1A3 in gastric cancer." (PMID 39394200, 2024). "However, the prognosis of gastric cancer patients with high ALDH1A3 expression was obviously worse than those with low ALDH1A3 expression." (PMID 37483492, 2023). "In gastric cancer cells, ALDH1A3 knockdown reduced cell proliferation." (PMID 36672441, 2023). "ALDH1A3 imparts stemness, tumorigenicity, and Aldefluor activity in gastric cancer." (PMID 36672441, 2023). "Similarly, in gastric cancer, ALDH1A3-mediated 5-fluorouracil resistance was connected to ALDH1A3 effects on gene expression of the mammalian target of mTOR and phosphorylation of mTOR target S6 kinase." (PMID 36672441, 2023). "Similarly, in colon and gastric cancers, reduced ALDH1A3 resulted in decreased colony formation." (PMID 36672441, 2023). "Concerning the epigenetic regulation of ALDH1A3 expression, feed-forward regulation between a histone demethylase, KDM4C, and ALDH1A3 has been reported in gastric cancer stem cells." (PMID 38669046, 2024). "In gastric cancer DTP cells, we found that an increase in H3K27ac and BRD4, acetylated histone-dependent modifiers, was critical for the expression of ALDH1A3, a DTP survival factor." (PMID 38669046, 2024). "In gastric cancer PDCs, we confirmed that BET inhibitors suppressed c-MYC expression in parental and DTP cells, whereas ALDH1A3 expression and cell survival were more preferentially suppressed in DTP cells than in parental cells." (PMID 38669046, 2024). "ALDH1A3 and ALDH1L1 are found to be significantly correlated to the worsened overall survival for all patients with gastric cancer and are potential prognostic markers and therapeutic targets for patients with gastric cancer." (PMID 29416787, 2018).
gastric cancer (continued). "To evaluate the effects of anticancer drugs on ALDH1A3 expression in a clinical context, we analyzed ALDH1A3 expression in FFPE tissues from 40 gastric cancers, including 20 cases treated with NAC with fluoropyrimidines and platinum agents and 20 treatment-naïve cases." (PMID 38669046, 2024).
Anophthalmia (8 papers, 2014 to 2023). Absence of the globe or eyeball. "The application of modern genomic technologies in our families enabled an accurate molecular diagnosis of ALDH1A3-associated anophthalmia/ microphthalmia to be established and has facilitated informed genetic counselling." (PMID 30200890, 2018). "Individuals with the same ALDH1A3 variant can display both anophthalmia and microphthalmia in different eyes, and affected individuals with the same mutation within the same family have been found to have clinical phenotypes of differing severity." (PMID 30200890, 2018). "Given that ALDH1A3 gene mutations appear to be the most common cause of anophthalmia and microphthalmia in consanguineous families, screening for variants in this gene before exome analysis in populations with high rates of consanguinity should be considered." (PMID 30200890, 2018). "This study expands the molecular spectrum of pathogenic ALDH1A3 variants associated with anophthalmia and microphthalmia, and provides further insight of the key role of the ALDH1A3 in human eye development." (PMID 30200890, 2018). "Occasionally, patients with ALDH1A3-associated anophthalmia and microphthalmia are also reported to have neurocognitive or behavioral features including intellectual disability, developmental delay and autism." (PMID 30200890, 2018). "There is a high variability observed in the phenotypic expression of dysmorphic or extra ocular features associated with anophthalmia and microphthalmia, even in individuals with the same ALDH1A3 genetic variants." (PMID 30200890, 2018). "Mild hypoplasia of the vermis (variant of Dandy-Walker malformation), as well as pulmonary stenosis and atrial septal defect, have also been reported in association with ALDH1A3-associated anophthalmia and microphthalmia." (PMID 30200890, 2018). "Knockout of Aldh1family members in mouse models causes congenital eye malformations such as uveal coloboma/optic fissure closure defects and biallelic mutations in ALDH1A3 in humans cause microphthalmia/anophthalmia." (PMID 25004007, 2014). "More recently recessive mutation in ALDH1A3 have been associated with severe micropthalmia, anophthalmia, and hypoplasia of the optic tract." (PMID 25004007, 2014). "Here, we show that genes previously linked with microphthalmia, including aldh1a3, rx2, six6b, vsx2, and recently mab21l2 with anophthalmia, are constitutive elements of an Rx3-regulated gene network." (PMID 25266257, 2014). "Interestingly, the same variant has been previously reported in four affected members of a family who presented with bilateral anophthalmia and facial dysmorphism, but normal psychomotor development, bringing into question the link between ALDH1A3 variants and intellectual and developmental delay." (PMID 36997679, 2023). "Although extraocular features have been reported in association with ALDH1A3-associated ocular disease, these are uncommon, and the associations are controversial, providing a relatively good prognosis for affected families when compared to other known causes of anophthalmia." (PMID 30200890, 2018). "Single-gene deletions and mutations affecting the ability to produce proteins and enzymes such as SOX2, MFRP, ALDH1A3, STRA6, PAX2, and OTX2, have been identified as causing isolated microphthalmia and anophthalmia and syndromic forms." (PMID 30153864, 2018). "Recently, Liu and coworkers identified compound heterozygous variants in ALDH1A3 in a proband from a non-consanguineous family with anophthalmia." (PMID 30200890, 2018). "In this study, we identified homozygous novel missense and frameshift sequence alterations in ALDH1A3 that segregate with the disease phenotype in consanguineous Pakistani families with isolated anophthalmia, and discuss our findings alongside existing literature in this area." (PMID 30200890, 2018).
Anophthalmia (continued). "It has previously been suggested that the difference in phenotype between microphthalmia and anophthalmia may be the result of residual ALDH1A3 activity." (PMID 30200890, 2018). "Loss of the ALDH1A3 gene causes anophthalmia in human, but not in mice." (PMID 26343735, 2015). "If the mouse model is the only source of information, it may be concluded that ALDH1A3 and RARβ play no role in anophthalmia and that ABCA4 plays no role in retinitis pigmentosa." (PMID 26343735, 2015).
microphthalmia (8 papers, 2014 to 2023). Congenital or developmental anomaly in which the eyeballs are abnormally small. "Since then, mutations of ALDH1A3 have been identified as a cause of autosomal recessive anophthalmia and microphthalmia in 54 individuals to date." (PMID 30200890, 2018). "Biallelic ALDH1A3 gene variants are the leading genetic causes of autosomal recessive anophthalmia and microphthalmia in countries with frequent parental consanguinity." (PMID 30200890, 2018). "Genes down-regulated in rx3-/- mutants are mostly associated with eye diseases, including microphthalmia (rx2, rx3, vsx2, six6b and aldh1a3) and oculoauricular syndrome (hmx1)." (PMID 25266257, 2014). "Mutations in the aldehyde dehydrogenase 1 family, member A3 (ALDH1A3) gene have been found in association with autosomal recessive anophthalmia and microphthalmia in individuals of different ethnicities." (PMID 30200890, 2018). "A similar search of DR17 using the term microphthalmia resulted in 22 genes significant for the small eyes phenotype: Aldh1a3, Aff4, Bmp4, Cdk4, Cox6b1, Cxcr4, Dync1li1, Eef1d, Fgd1, Gne, Grh12, Mab21l2, Maf, Med13l, Mllt10, Mthfd2, Pex6, Phgdh, Ssr1, Stim1, Tdo2, and Vps26c." (PMID 36737727, 2023). "Interestingly, genes involved in microphthalmia (VAX1, ALDH1A3, GJA1, and SMOC1) and retinal dystrophies (ADAMTS9, KCNJ13, CA2 and ABCA4) were also selected." (PMID 37479765, 2023). "Several mouse mutant lines are available for Aldh1a3, and they suffer from various eye diseases, but microphthalmia is not a term, which is used to characterize their phenotype." (PMID 30919050, 2019).
non-small cell lung carcinoma (8 papers, 2016 to 2024). A group of at least three distinct histological types of lung cancer, including non-small cell squamous cell carcinoma, adenocarcinoma, and large cell carcinoma. "Knockdown of ALDH1A3 led to decreased clonogenicity in neuroblastoma and non-small-cell lung carcinoma, whereas ALDHhigh cells were associated with increased clonogenicity in Ewing’s sarcoma." (PMID 35408953, 2022). "Additionally, ALDH1A3 expression was reported to be enriched in EGFR-mutated non-small cell lung carcinoma cells resistant to the EGFR tyrosine kinase inhibitor erlotinib, suggesting that ALDH1A3-expressing cancer cells are resistant to other treatments beyond chemotherapy." (PMID 36672441, 2023). "It is well appreciated that ALDH1A3 is an important driver of stemness in multiple cancer types, including breast, melanoma, glioblastoma, prostate, non-small cell lung cancer (NSCLC), head and neck cancer, and colon cancer." (PMID 38612911, 2024). "DIMATE, an irreversible inhibitor of ALDH1A1 and ALDH1A3, was cytotoxic for non-small cell lung cancer cell lines and effective against orthotopic xenografts and enhanced cisplatin chemotherapy." (PMID 36768694, 2023). "Profiling the ALDH isoforms by gene expression and knockdown in non-small cell lung cancer similarly revealed the importance of ALDH1A3 in the Aldefluor activity of cancer and tumorigenicity." (PMID 36672441, 2023). "In particular, ALDH1A3 targeting has been investigated for its potential clinical applications in several cancer types, including metastatic breast cancer, non-small-cell lung cancer (NSCLC) and mesenchymal subtype gliomas." (PMID 34641313, 2021). "Limited studies by us and others have suggested that ALDH1A3 supports stemness in GSCs by promoting glycolysis/gluconeogenesis, and is associated with higher Stat3 signaling in ALDH1+ CSCs derived from non-small cell lung cancer." (PMID 28423611, 2017). "In non-small cell lung cancer, tumorigenicity was reduced upon ALDH1A3 knockdown." (PMID 36672441, 2023). "However, low expression of ALDH1A3 is associated with non-small cell lung cancer (NSCLC), non-muscle invasive bladder cancer (NMIBC), and prostate cancer." (PMID 35454946, 2022). "There is gene amplification of ALDH1A1, ALDH1A3, or ALDH3A1 or upregulation of mRNA in 31% of non-small cell lung cancers." (PMID 36768694, 2023).
triple-negative breast carcinoma (8 papers, 2015 to 2026). An invasive breast carcinoma which is negative for expression of estrogen receptor (ER), progesterone receptor (PR), and human epidermal growth factor receptor 2 (HER2). "We observed an increase of Nanog only in MDA-MB-231 and SUM159PT triple-negative breast cancer cells and an increase of Notch1, Aldh1a1 and Aldh1a3 only in the SUM159PT cell line." (PMID 32610610, 2020). "Mucin 4 (MUC4), a potential oncogene with a RARE, inducible by RA, and associated with triple-negative breast cancer, is significantly induced by ALDH1A3 and RA in MDA-MB-231 cells, but not in MDA-MB-468 cells." (PMID 31590252, 2019). "Aldehyde dehydrogenase 1A3 (ALDH1A3) promotes tumor growth, metastasis, and chemoresistance in multiple cancers, including triple-negative breast cancer (TNBC), yet no clinically approved, isoform-selective inhibitors exist." (PMID 41797928, 2026).